OR5B2 (olfactory receptor family 5 subfamily B member 2)
Description:
Odorant receptor.
Synonyms: OST073; OR11-240
Tractability: Antibody: UniProt places it where antibodies can reach, with medium confidence; UniProt predicts a signal peptide or a membrane-spanning region; its Gene Ontology location is reachable by antibodies, with medium confidence.
Gene: Protein-coding gene on chromosome 11 (58,421,238 to 58,428,121, reverse strand). Ensembl gene ENSG00000172365.
Subcellular location: Cell membrane
Pathways (Reactome):
Sensory Perception: Expression and translocation of olfactory receptors
Gene Ontology:
Molecular function: olfactory receptor activity; G protein-coupled receptor activity
Biological process: G protein-coupled receptor signaling pathway; sensory perception of smell; detection of chemical stimulus involved in sensory perception of smell
Cellular component: plasma membrane; membrane
Genetic constraint (gnomAD): Missense variants: 406 observed, 379.34 expected, observed/expected ratio (o/e) 1.07, 90% interval 0.99 to 1.16. Synonymous variants: 159 observed, 145.85 expected, observed/expected ratio (o/e) 1.09, 90% interval 0.96 to 1.24.
Homologues: Orthologues: chimpanzee OR5B2 (96% identical), macaque OR5B2 (94% identical), rabbit OR5B2 (80% identical), dog OR5B2 (75% identical), rat Or5b99 (73% identical), mouse Or5b99 (73% identical). Paralogues in human: OR5B3 (77% identical), OR5B12 (73% identical), OR5B17 (71% identical), OR5B21 (67% identical), OR8U1 (53% identical), OR5AR1 (51% identical), OR5F1 (51% identical), OR9I1 (51% identical), OR8I2 (50% identical), OR5AP2 (50% identical), OR5AU1 (50% identical), OR5L1 (50% identical), and 84 more.